NOX4 (NADPH oxidase 4)
Diseases named in the same sentence as NOX4 in open-access papers (continued):
Sharing a sentence is not in itself a finding about the gene and the disease.
breast carcinoma (continued). "Other studies have suggested that NADPH oxidase NOX4 promotes carcinogenesis and protects breast cancer cells from anoikis." (PMID 29478325, 2019). "NOX4 was also detected in a significant proportion of small cell lung carcinomas (11/12, 92%), gastric carcinomas (12/17, 71%) and breast carcinomas (18/20, 90%)." (PMID 28578276, 2017). "Previously, it has been shown that TGF-β1 consistently up-regulates Nox4 expression via Smad 2/3-dependent pathways in fibroblasts, human pulmonary artery smooth muscle cells and breast cancer cells." (PMID 24629065, 2014). "Specifically, prolonged GLP-1RA administration (1–3 years or longer) has been associated with elevated thyroid cancer risk in certain populations, while high concentrations of liraglutide (100 nM) have been demonstrated to promote breast cancer progression via the NOX4/ROS/VEGF signaling pathway." (PMID 40140925, 2025). "Therapeutically targeting the NOX4-MYC axis and leveraging NOX4's immunomodulatory capacity could offer promising strategies for breast cancer management." (PMID 39991149, 2025). "Furthermore, the treatment enhanced the levels of cytosolic Ca2+ and ROS and upregulated NOX4 in breast cancer cells." (PMID 39770941, 2024). "Cannabidiol has been found to induce NOX4-mediated release of mitochondrial ROS and promote caspase-dependent apoptosis through the activation of ER stress signaling pathway and the inhibition of the mTOR signaling pathway in breast cancer cells." (PMID 39796030, 2024). "This study also investigated the effects of NOX4 on the glycolysis of breast cancer in vivo." (PMID 37670970, 2023). "We then clarified whether NOX4 influenced the glycolysis and migration of breast cancer through the ROS/YAP pathway." (PMID 37670970, 2023). "In summary, NOX4 is closely related to the proliferation and migration of breast cancer cells." (PMID 37670970, 2023). "It investigated how NOX4 affected breast carcinoma cells’ biological morphology and stemness." (PMID 38012557, 2023). "Conversely, following the overexpression of NOX4, the expression of these key glycolysis enzymes increased, indicating that NOX4 could regulate glycolysis of breast cancer." (PMID 37670970, 2023). "In addition, JI017 induces apoptosis and ER stress and overcomes paclitaxel resistance by increasing ROS and Nox4 expression in breast cancer cells." (PMID 36830050, 2023). "Nox4 activation by nodakenin treatment induced ROS and Ca2+ release, ER stress, and apoptotic cell death in breast cancer cell lines; however, Nox4 knockdown blocked ER stress and apoptotic cell death via ROS and Ca2+ release in nodakenin-treated breast cancer cell lines." (PMID 36830050, 2023). "Taken together, our study strongly supports a role of Nox4 in breast CAFs and that this pro-oxidant could be a promising stroma target to interfere with the tumor supporting network in breast cancer." (PMID 35836253, 2022). "Moreover, in comparison to all the Nox enzymes, Nox4 is up-regulated most extensively in breast cancer stroma across all stroma studies." (PMID 35836253, 2022). "We found that stroma deletion of Nox4 and administration of a pharmaceutical Nox4 inhibitor (GKT137831) resulted in suppression of orthotopic mammary tumor growth and metastasis in two syngeneic models, suggesting a prominent role of stroma Nox4 in oncogenesis." (PMID 35836253, 2022). "In addition, we investigated whether NOX4 promotes proliferation and migration of breast cancer cells through glycolysis." (PMID 37670970, 2023). "Furthermore, we explored whether NOX4 could affect the glycolysis and proliferation and migration of breast cancer through the ROS/YAP pathway." (PMID 37670970, 2023). "The involvement of NOX4 in glycolysis in breast cancer remains unclear." (PMID 37670970, 2023).
breast carcinoma (continued). "Furthermore, Oncomine analysis showed that Nox4 is ranked in the top 1–3% of most significantly upregulated genes in breast carcinoma stroma versus normal stroma, whereas only a slight upregulation is seen in breast cancer epithelial cells." (PMID 35836253, 2022). "Silencing NOX4 or antioxidant (DPI or NAC) treatment reduced the enhancements in intracellular ROS, cytotoxicity, and caspase-3 activity in KA-treated breast cancer cells, indicating NOX4 as the regulator of KA-induced ROS generation." (PMID 39770941, 2024). "Since there is a relationship between ROS and NADPH Oxidase 4 (NOX4), Nox4 ablation blocked ER stress-mediated apoptotic cell death by inhibiting ROS release in FAD-induced breast cancer models." (PMID 39765861, 2024). "NOX4 affects breast cancer glycolysis through ROS-induced activation of the YAP pathway, further promoting the proliferation and migration of breast cancer cells." (PMID 37670970, 2023). "NOX4 activates the YAP pathway through ROS, which in turn influences breast cancer glycolysis, further promoting breast cancer proliferation and migration." (PMID 37670970, 2023). "Using the 3 CRISPR method, shRNA that targeted NOX4 and enhanced expression vectors were added to MDA-MB-231 and MCF-7 human breast cancer cells to reduce or boost expression." (PMID 38012557, 2023). "Overexpression of NOX4 activated YAP and the glycolysis and proliferation and migration of breast cancer cells were enhanced." (PMID 37670970, 2023). "The results suggested that NOX4 contributed to the maintenance of breast cancer CSC characteristics and that NOX4 was involved in breast cancer cell proliferation and differentiation." (PMID 38012557, 2023). "NOX4 is overexpressed in several types of cancer including breast cancer and kidney cancer, non-small cell lung cancer (NSCLC) where ROS generated by NOX4 promote cell proliferation and cancer metastasis." (PMID 36670929, 2022). "Our findings suggest that Nox4 is involved in ER stress and apoptotic cell death by ROS production in JI017-treated breast cancer cells." (PMID 34942984, 2021). "The overexpression of iNOS, nNOS, CAR, KEAP1, NOX4, and TGR5 or the downregulation of NRF2 correlated with better survival in breast cancer patients, except for triple negative cases." (PMID 31461945, 2019). "In conjunction with the NAPDH oxidase NOX4, SOD2 contributes to breast cancer progression at late stage III by promoting AMPK phosphorylation at Thr172." (PMID 29478325, 2019). "Previous research has shown that Schisandrin B, a novel inhibitor of NOX4, inhibits EMT and attenuates breast cancer cell metastasis." (PMID 28422720, 2017). "Curcumin mediates NOX4-induced mitochondrial ROS and then it also induces caspase-dependent apoptotic cell death through the reduction in c-FLIP and Mcl-1 expression in head and neck squamous cell carcinoma, human breast cancer, and human glioma cells." (PMID 41465451, 2025). "However, in highly invasive breast cancer cell lines MDA-MB-231 and MDA-MB-468, high concentrations (100 nM) of liraglutide promote breast cancer progression by activating GLP-1R via the NOX4/ROS/VEGF signaling pathway." (PMID 40140925, 2025). "Therefore, this study aimed to identify a breast tumor therapeutic that overcomes radioresistance by activating Nox4 and ER stress-induced apoptotic cell death in FAD-treated breast cancer and radioresistant breast cancer cells." (PMID 39765861, 2024).
breast carcinoma (continued). "NOX4 silencing or antioxidant (NAC or DPI) treatment reduced the enhancement in intracellular ROS, caspase-3 activity, cytotoxicity, and the PERK-ATF4-CHOP signaling pathway in KA-treated breast cancer cells." (PMID 39770941, 2024). "However, the inhibition of Nox4 and the treatment with the ROS inhibitor DPI or NAC suppressed intracellular Ca2+ and ROS production, apoptosis, and UPR response in FAD-treated breast cancer cells." (PMID 39765861, 2024). "We found that deletion of stroma Nox4 and pharmaceutically targeting its activity with GKT137831 significantly inhibited orthotopic tumor growth and metastasis of implanted E0771 and 4T1 murine mammary carcinoma cell lines in mice." (PMID 35836253, 2022). "To date, not much is known about the role of Nox4 in breast cancer despite a few studies showing that overexpression of this enzyme in cancer cells can promote an aggressive phenotype." (PMID 35836253, 2022). "We sought to examine whether JI017 mediates apoptosis via Nox4 expression, ROS and Ca2+ production, and the PERK–ATF4–CHOP axis in breast cancer cells." (PMID 34942984, 2021). "Moreover, TGF-β induces NOX4-dependent ROS production, which contributes to the EMT and cells migration in breast cancer cells." (PMID 26904167, 2016). "Thus, the expression of downstream NOX4/ROS/VEGF signaling pathway-related proteins is activated and the proliferation of breast cancer cells is increased, whereas the proliferation of breast cancer cells is inhibited in the control group with the addition of inhibitors." (PMID 39371922, 2024). "Furthermore, a NOX4 knockdown combined with a DPI or NAC treatment blocked the inhibition of cell viability and the enhancement in intracellular ROS, cytotoxicity LDH, and colorimetric caspase-3 activity in FAD-induced breast cancer cell lines." (PMID 39765861, 2024). "However, the impact and mechanism of NOX4 activity in glycolysis of breast cancer cells has not been studied." (PMID 37670970, 2023). "NOX4 may function as an oncogene in a variety of tumors, such as pancreatic cancer, breast cancer, and lung cancer; however, its potential role in OS has not been reported before." (PMID 36225939, 2022). "TGF-β increases the expression of the Nox4 gene, which contributes to ROS production through a Smad3-dependent mechanism, and it might be significant for the development of TGF-β-generated EMT in breast cancer." (PMID 34947978, 2021). "Since lower concentrations of NO reduced proliferation of AA breast cancer cell lines, we further examined its effect on Mn SOD and Cu/Zn SOD as well as on various proliferation (cyclin D1 and PCNA), apoptosis (Bax and Bcl2), and oxidative stress (NOX4) markers." (PMID 27473585, 2016). "However, in breast cancer, the effect of NOX4 on glycolysis has not been confirmed." (PMID 37670970, 2023). "HER2 monoclonal antibody trastuzumab has achieved exciting results in the treatment of breast cancer; however, Phase II clinical trials confirmed that trastuzumab is not effective in the treatment of ovarian cancer, which may be due to this novel HIF-1/NOX4 pathway." (PMID 34209278, 2021). "While these small number of studies support a tumor-promoting role of Nox4 derived from activated fibroblasts, direct evidence linking this pro-oxidant to the tumor-supporting CAF phenotype and the mechanisms involved is lacking, particularly in breast cancer." (PMID 35836253, 2022). "While there are a small number of studies suggesting an oncogenic role of Nox4 derived from activated fibroblasts, direct evidence linking this pro-oxidant to the tumor-supporting CAF phenotype and the mechanisms involved are lacking, particularly in breast cancer." (PMID 35836253, 2022).
Hyperglycemia (48 papers, 2012 to 2025). An increased concentration of glucose in the blood. "Hyperglycemia induces mtROS via the NADPH oxidase 4 (NOX4)/TRPC6 axis, causing oxidative stress, mtDNA damage, and ATP loss." (PMID 41009719, 2025). "Hyperglycemia enhanced the interaction between NF-κB/p65 and the NOX4 promoter, underlying the significant elevations in NOX4 mRNA and protein expression as well as increased ROS levels compared with normal glucose concentrations." (PMID 31382355, 2019). "Hence, this study elucidated that the mechanism of hyperglycemia-associated NOX4 expression occurs via NF-κB/p65 transcription." (PMID 31382355, 2019). "Additionally, in stroke complicated by obesity and hyperglycemia, increased NOX4 expression may be associated with functional deficits, while elevated blood glucose levels after stroke may contribute to increased superoxide production through NOX2 activation." (PMID 39334724, 2024). "Moreover, hyperglycaemia caused more pronounced changes in 3D cultures than in 2D cultures, including bigger and a greater number of spheroids, upregulation of NOX4 and the apoptotic proteins NF-κB and CASP3, and downregulation of fibronectin and transglutaminase-2." (PMID 36830559, 2023). "In diabetic Akita mice, hyperglycemia and hyperhomocysteinemia led to increased cardiac expression of NOX4, contributing to cardiac remodeling; treatment with the antioxidant tempol reduced NOX4 expression and reversed the remodeling." (PMID 41009041, 2025). "In particular, TGF-β induces (NOX)-4 and hyperglycemia enhances NOX4-mediated ROS production, which activates the TGF-β1-Smad2/3 pathway, leading to EndMT and ECs fibrosis/apoptosis." (PMID 40650130, 2025). "Further, the crucial contribution of mitochondrial Nox system especially, Nox4 has been suggested to trigger oxidative stress in hyperglycemia including in T1DN." (PMID 38835661, 2024). "NOX-4 is a membrane-bound enzyme that utilizes oxygen and generates reactive oxygen species during hyperglycaemia." (PMID 39166118, 2024). "A recent in vitro study reported in the year 2019 by Yu T and co-workers showed the role of NOX-4 in the hyperglycaemia-induced apoptosis of Schwann cells which were involved in the development of diabetic peripheral neuropathy." (PMID 39166118, 2024). "Third, sulodexide prevented hyperglycemia-induced overexpression of the pro-oxidant enzymes, NOX4 and NOX5, in the vascular wall." (PMID 36829947, 2023). "Intriguingly, immunoreactivity not only to NOX5 but also to NOX 4 was increased in retinal arterioles exposed to hyperglycemia, suggesting glucose-dependent upregulation of NOX4 and NOX5." (PMID 36829947, 2023). "Although sulodexide itself had only negligible antioxidant properties, it prevented hyperglycemia-induced overexpression of the pro-oxidant redox enzymes NOX4 and NOX5." (PMID 36829947, 2023). "Hyperglycemia can activate NADPH oxidase 4 (NOX4) and produce reactive oxygen species (ROS) in the liver." (PMID 38001866, 2023). "To this end, we evaluated the levels of NOX2 and NOX4, the main enzymes involved in the production of ROS induced by hyperglycaemia." (PMID 35204314, 2022). "Constitutively active NADPH oxidase 4 (Nox4) is a major source of ROS that mediates hyperglycemia-induced mesangial cell (MC) fibrotic injury." (PMID 35597446, 2022). "Consistent with this concept, our findings showed that Sal B prevents podocyte injury via targeting of mitochondrial NOX4 mediated ROS generation under hyperglycaemia conditions." (PMID 33332718, 2021). "The upregulation of NOX4 expression with hyperglycemia was attenuated by pharmacological inhibition of NF-κB/p65 via caffeic acid phenethyl ester (CAPE) and siRNA against NF-κB/p65." (PMID 31382355, 2019). "In this regard, it was demonstrated that hyperglycemia leads to colocalization of NOX4 and mitochondrial superoxide in isolated rat kidney and cultured mesangial cells." (PMID 31382355, 2019).
Hyperglycemia (continued). "STAT3 activation is also known to be involved in hyperglycaemia-induced endoplasmic reticulum stress in endothelial cells; inhibiting NOX4 can attenuate high-glucose induced reactive oxygen species (ROS) generation and STAT3 activation." (PMID 31286987, 2019). "We showed that hyperglycemia mediated the upregulation of NOX4, p47phox and Rac-1 protein levels, which were significantly reduced by GLP-1." (PMID 28808291, 2017). "It has also been reported that Nox4 is upregulated in an animal diabetic model or as a result of hyperglycemia, with a concomitant increase in ROS." (PMID 24485356, 2014). "Our data additionally revealed Nox4-induced ROS generation, hyperglycemia-induced mitochondrial dysfunction leading to reduced antioxidant capacity, NFAT5 overexpression, and glucose-induced upregulation of EGR1." (PMID 23149823, 2013). "Hyperglycemia increased oxidant stress and Nox4 expression in MSCs, but the oxidant stress increased to a lesser extent than that induced by hyperinsulinemia." (PMID 23316315, 2012). "In μg-conditions resulting in detached cellular structures, including spheroids and multicellular structures, hyperglycaemia increased the size and the number of spheroid structures, decreased fibronectin and transglutaminase-2, and increased NF-κB, NOX4, and caspase-3." (PMID 36830559, 2023). "Remarkably, sulodexide prevented hyperglycemia-induced NOX4 and NOX5 expression in the vascular wall, suggesting that this may be one of the mechanisms preventing ROS generation." (PMID 36829947, 2023). "Exposure to hyperglycemia, the expression of NOX4 in mouse proximal renal tubular cells is increased, using NOX1/4 inhibitors (GKT136901) or NOX4 siRNA could block the damage of hyperglycemia to kidney, and reduce the production of proteinuria." (PMID 35645822, 2022). "In still another intriguing body of work, the curtailment of microRNA-25 (miR-25) maturation by high glucose or TGFβ in mesangial cells or by hyperglycemia in diabetic kidney resulted in the reversal of NOX4 gene silencing leading to increased NOX4 expression and ROS production." (PMID 36670932, 2022). "A significant increase in the mRNA and protein levels of Nox1 (mRNA ≈ 3-fold; protein ≈ 2-fold), Nox2 (mRNA ≈ 2-fold; protein ≈ 2.7-fold), and Nox4 (mRNA ≈ 4-fold; protein ≈ 1.85-fold) isoforms were determined in the kidney of diabetic mice after 4 weeks of hyperglycaemia." (PMID 34572988, 2021). "Besides hyperglycemia-increased production of ROS and the modification of antioxidant mechanisms, the hyperinsulinemia-induced Nox4-derived oxidants also lead to altered BMMSC differentiation." (PMID 33572905, 2021). "Thus, XST protected against podocyte apoptosis partly by downregulation of Nox4 and miR-214 expression induced by hyperglycaemia." (PMID 32051833, 2020). "Several lines of evidence have demonstrated that the NADPH oxidases (including NOX2 and NOX4) are directly enhanced by the hyperglycemia in diabetic heart, indicating that ROS derived from NADPH oxidase might contribute to diabetic myocardial damage." (PMID 33308195, 2020). "We also hypothesized that hyperglycemia-induced mitochondria dysfunction is mediated by enhanced activity of PRR/NOX4 signaling pathway." (PMID 31406124, 2019). "In adipocytes and in early stages of T2DM, Nox4 activity may be stimulated by hyperglycemia via an increased flow through the pentose phosphate shuttle and augmented NADPH, and by palmitate via a TLR4-dependent mechanism." (PMID 30265686, 2018). "GKT137831 treatment showed an effective improvement in aorta relaxation, revealing that the inhibition of Nox4 could reverse endothelium-dependent relaxation suffered from hyperglycemia damage." (PMID 30135489, 2018). "Furthermore, the oxidative stress markers Nox1, Nox2, Nox4, and p47 in mRNA level were increased in DF, and consequently, it was suggested that oxidative stress is elevated in the gingival tissue by hyperglycemia." (PMID 29267310, 2017).